SULF2 (sulfatase 2)
Description:
Exhibits arylsulfatase activity and highly specific endoglucosamine-6-sulfatase activity. It can remove sulfate from the C-6 position of glucosamine within specific subregions of intact heparin.
Synonyms: hSulf-2; KIAA1247; SULF-2
Tractability: Antibody: UniProt places it where antibodies can reach, with high confidence; its Gene Ontology location is reachable by antibodies, with high confidence; UniProt predicts a signal peptide or a membrane-spanning region. PROTAC: ubiquitination databases record sites on it; its protein half-life has been measured.
Gene: Protein-coding gene on chromosome 20 (47,656,197 to 47,786,835, reverse strand). Ensembl gene ENSG00000196562.
Subcellular location: Endoplasmic reticulum; Golgi apparatus, Golgi stack; Cell surface; Secreted (Extracellular sulfatase Sulf-2 secreted form)
Gene Ontology:
Molecular function: arylsulfatase activity; N-acetylglucosamine-6-sulfatase activity; protein binding; calcium ion binding; sulfuric ester hydrolase activity
Biological process: heparan sulfate proteoglycan metabolic process; positive regulation of Wnt signaling pathway; bone development; cartilage development; chondrocyte development; embryonic skeletal system development; esophagus smooth muscle contraction; glial cell-derived neurotrophic factor receptor signaling pathway; glomerular basement membrane development; glomerular filtration; heparan sulfate proteoglycan catabolic process; innervation; kidney development; negative regulation of fibroblast growth factor receptor signaling pathway; positive regulation of vascular endothelial growth factor production; positive regulation of endothelin production
Cellular component: cell surface; endoplasmic reticulum; extracellular region; plasma membrane; Golgi apparatus; Golgi stack
Genetic constraint (gnomAD): Loss-of-function variants: 49 observed, 101.25 expected, observed/expected ratio (o/e) 0.48, 90% interval 0.38 to 0.61. The upper end of that interval is the gene's LOEUF score, 0.61, which puts it in group 2 of 6, group 1 being the genes least tolerant of losing a copy. Missense variants: 986 observed, 1,153.5 expected, observed/expected ratio (o/e) 0.85, 90% interval 0.81 to 0.9. Synonymous variants: 459 observed, 447.86 expected, observed/expected ratio (o/e) 1.02, 90% interval 0.95 to 1.11.
Homologues: Orthologues: chimpanzee SULF2 (99% identical), macaque SULF2 (99% identical), dog SULF2 (96% identical), pig SULF2 (95% identical), guinea pig SULF2 (95% identical), mouse Sulf2 (94% identical), rat Sulf2 (94% identical), rabbit SULF2 (85% identical), tropical clawed frog sulf2 (82% identical), zebrafish sulf2b (73% identical), Drosophila melanogaster Sulf1 (43% identical), Caenorhabditis elegans sul-1 (37% identical), and 6 more. Paralogues in human: SULF1 (64% identical), GNS (27% identical), STS (14% identical), ARSL (14% identical), ARSD (13% identical), ARSH (13% identical), ARSF (13% identical), ARSI (13% identical), ARSJ (13% identical), GALNS (13% identical), ARSK (13% identical), ARSG (12% identical), and 4 more.
Diseases named in the same sentence as SULF2 in open-access papers:
SULF2 is named in the same sentence as 90 diseases in open-access papers, as found by Europe PMC text mining. Sharing a sentence is not in itself a finding about the gene and the disease. The quoted sentences say what the papers report.
breast carcinoma (21 papers, 2006 to 2025). "In particular, SULF2 has been directly implicated as a candidate cancer-causing gene in human breast cancer and mouse brain cancer." (PMID 26882224, 2016). "We have shown previously that HNSCC tumors express higher amounts of the SULF2 protein and other studies documented that the distribution of SULF2 in several cancer diseases (non-small cell lung cancer, esophageal cancer, hepatocellular carcinoma or breast cancer) is associated with poor survival." (PMID 33585200, 2020). "SULF2 may act as a breast cancer suppressor, and knock-down of SULF2 in cell lines causes tumorigenic phenotypes, including increased proliferation, enhanced survival, and increased anchorage-independent growth." (PMID 27506935, 2016). "Coincidently, other reports have also proven the important role of SULF2 in the progression of other tumors, such as lung cancer, breast cancer, and prostate cancer." (PMID 32049100, 2020). "A various amount of evidence supports this point of view, where sulfatase 2 (SULF2) was elevated in breast cancer and HCC." (PMID 33344222, 2020). "Conversely, silencing of Sulf2 expression in breast cancer cells attenuated ductal carcinoma in situ progression to invasive ductal carcinoma in vivo." (PMID 25105093, 2014). "As previously observed for several breast carcinoma cell lines, Sulf-2 protein was detected in CM as a processed 75 kDa component." (PMID 17460759, 2007). "Upregulation of Sulf-2 at both the transcript and protein levels has been established in two mouse models of mammary carcinoma." (PMID 16417632, 2006). "Here, we have taken advantage of recombinant Sulf-2 generated in 293 cells and of native Sulf-2 obtained from conditioned medium of a breast carcinoma cell line to explore the range of activities for this enzyme." (PMID 16417632, 2006). "Furthermore, we found that there was a statistically significant difference between the percentages of cells that were positive for SULF2 in tissue sections of TNBC breast cancer stages 2A vs. 2B." (PMID 40140347, 2025). "It has been shown that sulfatase 2 (Sulf2) downregulates PDGF-C expression in breast cancer." (PMID 34847773, 2021). "The SULF2 gene is located on human chromosome 20q13, which has been reported to play important roles in various cancers, including liver cancer, gastric cancer, kidney cancer, breast cancer, and non-small cell lung cancer." (PMID 32049100, 2020). "Moreover, proteasomal inhibitors such as bortezomib abolished Sulf2 expression in multiple breast cancer cells." (PMID 25105093, 2014). "As such, the upregulation of two cell-surface PGs, glypican-1 (GPC1) and syndecan-1 (SDC1), and of the extracellular sulfatase Sulf-2, have been described in malignant breast cancer tissues whilst the downregulation of some genes including SULF1 and HS3ST2 has also been reported." (PMID 23327652, 2013). "Thus, for example, SULF1 is upregulated in significant subsets of breast cancer, pancreatic cancer lung adenocarcinoma and hepatocellular carcinoma, while SULF2 is upregulated in multiple myeloma, breast cancer and CNS cancers." (PMID 17460759, 2007). "With regard to breast cancer, previous studies indicate an upregulation of SULF2, while SULF1 has been found to be down regulated in some breast cancer cell lines, although in our study we could only detect a small reduced relative abundance of mRNA of SULF1 in less than 10% of the cases analyzed." (PMID 23327652, 2013). "Thus, the observed upregulation of Sulf-2 in mammary carcinomas and its secretion from these cells could directly contribute to tumor angiogenesis and thus tumor growth." (PMID 16417632, 2006). "We determined that there was a statistically significant difference between breast cancer sub-types TNBC and ER+/PR+ and TNBC and HER2+, in the percentages of cells that stained moderately or strongly positive for SULF2." (PMID 40140347, 2025).
breast carcinoma (continued). "The expression of SULF2 was compared between TNBCs, ER+/PR+, HER2+ breast cancer, normal breast tissue, and DCIS." (PMID 40140347, 2025). "An AMSBIO BR1202B breast cancer tissue array (120 cores with 82 TNBC cores, 20 ER+/PR+ cores, 14 HER2+ cores, and 4 necrotic cores) was stained with SULF2." (PMID 40140347, 2025). "Additional statistical analysis was carried out comparing the SULF2 expression among TNBCs, ER+/PR+, HER2+ breast cancer, normal breast tissue, and DCIS." (PMID 40140347, 2025). "ARFGEF2:SULF2 fusion was also called for MCF-7 cell line and SLC27A6:ADAMTS19 was previously identified in breast cancer with short reads." (PMID 35164688, 2022). "Human sulfatase-2 (SULF2), an HS 6-O-endosulfatase, was found to inhibit in vivo tumor growth in human breast cancer xenograft models." (PMID 31013618, 2019). "One of these fusions, SULF2--ZNF217 predicted by nine different methods in cell line MCF7, was recently predicted to be a potential driver of breast cancer." (PMID 31639029, 2019). "We established a model of stable expression of sulfatases in the human breast cancer cell line MDA-MB-231 and purified recombinant human Sulfatase 2 (rhSulf2) for exogenous administration." (PMID 20707913, 2010). "Interestingly, SULF2 increases cell proliferation, invasion, mobility, and adhesion in MCF-7 and MDA-MB-231 breast cancer cell lines." (PMID 34502082, 2021). "But, to date, recombinant human Sulfatase 2 effect on breast cancer cells has not been tested in vitro or in vivo." (PMID 20707913, 2010). "Upregulation of SULF2, as shown here in HNSCC, has been reported in a range of tumors including pancreatic adenocarcinoma, hepatocellular carcinomas, lung adenocarcinoma, lung squamous cell carcinoma, esophageal carcinomas and human breast cancer and hyperplastic tissues." (PMID 27223083, 2016). "Additionally, we observed a statistically significant difference between breast cancer sub-types TNBC and ER+/PR+ and TNBC and HER2+ of the average percentages of cells that stained negative or weakly positive for SULF2." (PMID 40140347, 2025).
hepatocellular carcinoma (16 papers, 2007 to 2022). A malignant tumor that arises from hepatocytes. "Here, we elucidated the role of SULF2 in the differentiation of hepatic stellate cells (HSCs) into carcinoma-associated fibroblasts (CAFs) in the hepatocellular carcinoma (HCC) microenvironment and the mechanism underlying CAF-mediated HCC growth." (PMID 33889573, 2021). "Moreover, SULF2 promoter methylation and expression has been associated with overall survival in lung cancer, gastric cancer, and hepatocellular carcinoma." (PMID 26882224, 2016). "Interestingly, the insensitivity of Sulf1 as well as Sulf2 deficient cerebellar cells to staurosporine-induced cell death is similar to what has been described for hepatocellular cancer as well as head and neck squamous cell carcinoma cell lines." (PMID 26448642, 2015). "Surprisingly, Sulf-2 overexpression in human hepatocellular carcinoma cells promoted TGF-β1 signaling." (PMID 32318065, 2020). "SULF2 functions as an oncoprotein in hepatocellular carcinoma and treatment with OKN-007 significantly decreased SULF2 activity, which is associated with PDGFRα expression." (PMID 33168005, 2020). "In hepatocellular cancer cell lines, overexpression of SULF2 led to increased proliferation and migration and markedly enhanced the tumorigenicity of these cells in nude mice." (PMID 26882224, 2016). "High SULF2 expression in hepatocellular carcinoma tumor tissue has also been shown to worsen prognosis and increase recurrence after surgery." (PMID 27223083, 2016). "Our current data showed that OKN-007 was able to significantly decrease the immunoexpression of SULF2 (p < 0.05) in responsive mice compared to untreated animals, which has also been recently demonstrated in hepatocellular cancer cells." (PMID 26248280, 2015). "SULF2 overexpression occurs in hepatocellular carcinoma (HCC)." (PMID 36589727, 2022). "SULF2 has been directly implicated as a driver of carcinogenesis in NSCLC, murine and human malignant glioma including glioblastoma and oligodendroglioma, pancreatic cancer, and hepatocellular carcinoma." (PMID 26882224, 2016). "The human sulfatase 2 (SULF2) inhibitor 2,4-disulfophenyl-N-tert-butylnitrone (OKN-007) exhibits antitumoral activity in hepatocellular carcinoma and glioblastoma by affecting TGFbeta1/SMAD signaling, and cell proliferation and angiogenesis, respectively." (PMID 32916872, 2020). "Consistent with their opposing roles in growth factor signaling, Sulf2 expression attenuated cell death induction by MEK, JNK, and PI3K inhibitors in hepatocellular carcinoma cell lines." (PMID 25105093, 2014).
lung carcinoma (11 papers, 2013 to 2024). "SULF2 (Sulfatase 2), lung cancer associate gene, has been shown to have increased total methylation status in sputum samples of ex-smokers showing lasting symptoms of COPD, which is chronic mucous hypersecretion (CMH)." (PMID 35008971, 2022). "Nevertheless, the results of this initial analysis provide evidence that early stage lung cancer is associated with an increased plasma concentration of SULF2." (PMID 26882224, 2016). "This proposed mechanism is consistent with a previous study in lung carcinoma cells, where siRNA or epigenetic silencing of SULF2 was found to activate expression of interferon-inducible genes." (PMID 39141086, 2024). "The increased expression of SULF2 and its impact on tumor biology and/or patient survival are already established in the case of breast, liver, esophageal, or lung cancers." (PMID 33585200, 2020). "To analyze the expression and function of SULF2 in vivo, we used H460 lung cancer cells, because these cells efficiently form tumors in mice, and we confirmed that SULF2 in H460 cells responds to IR." (PMID 26895473, 2016). "Together, these data suggests the potential of SULF2 protein as a prognostic biomarker in patients with lung cancer." (PMID 26882224, 2016). "Our results show that SULF2 was expressed in 72 of 93 human lung cancer tumors, including 25 of 41 (60%) adenocarcinoma samples and 51 of 51 (100%) squamous cell carcinoma samples." (PMID 26882224, 2016). "Moreover, in malignant astrocytoma, and pancreatic, colorectal, and lung cancer cell lines SULF2 knockdown led to reduced proliferation and decreased growth of xenografts in mice, likely due to its effect on signaling pathways induced by HSPG binding factors." (PMID 26882224, 2016). "SULF2 staining was present in 82% of the lung cancer samples." (PMID 26882224, 2016). "Widespread Sulf2 protein expression was identified in tumor cells of 10/10 surgical specimens of human lung squamous carcinomas and knockdown of Sulf2 was found to reduce the growth of lung cancer cells, inhibit autocrine Wnt signaling, and inhibit tumor progression in a mouse model of NSCLC." (PMID 25105093, 2014). "The authors concluded that not only should Sulf2 be considered as a potential biomarker of lung cancer but that its inhibition could be achievable via small molecule or biologic agents and thus should be considered as a therapeutic target in lung cancer." (PMID 25105093, 2014). "SULF2 knockdown reduced Wnt/ß-catenin signaling in THCE cells by ≈30%, which compares to 50–70% inhibition in pancreatic and lung cancer cell lines using the same methodology." (PMID 23950901, 2013). "A previous study revealed that exposure to 2 Gy IR did not significantly affect the growth of H460 lung cancer cells in a xenograft model but promoted SULF2 mRNA levels." (PMID 34440158, 2021). "Consistently, we found that exposure to 2 Gy IR, not 5 Gy, also promoted SULF2 mRNA expression in our lung metastasis model injected with A549 lung cancer cells via the tail vein." (PMID 34440158, 2021). "Interestingly, Human sulfatase-2 (SULF2), an HS 6-O-endosulfatase involved in modulating HS biological activities, and B4GALT7 have been previously found to promote, respectively, carcinogenesis and progression in lung cancers." (PMID 36362413, 2022).
pancreatic cancer (9 papers, 2007 to 2024). "It has been proposed that SULF-1 as well as SULF-2 are positive regulators of pancreatic cancer development through the Wnt signaling pathway." (PMID 36359323, 2022). "Taken together, heparanase, Sulf1, and Sulf2 are enzymes which appear, at least in pancreatic cancer, to be positive regulators of tumor development." (PMID 25105093, 2014). "SULF2, which was strongly up-regulated in both systems and acts to remove sulfates from certain GAG chains, also has been associated with lung carcinogenesis and the tumorigenicity of pancreatic cancer cells." (PMID 20885998, 2010). "Pancreatic cancer (PDAC) is the only CPTAC study with both SULF1 and SULF2 protein significantly upregulated >2-fold in tumors compared with paired normal tissues." (PMID 36428645, 2022). "The SULF2 protein is expressed in pancreatic cancer cells; both SULF1 and its homolog SULF2 have been shown to deferentially splice to regulate pancreatic tumor progression and have been proposed as both biomarkers and treatment targets." (PMID 33114263, 2020). "The finding that Sulf1 and Sulf2 can promote canonical Wnt signaling, a well described cascade in PDAC, suggests their overexpression is a contributory factor in relation to the growth and tumorigenicity of these pancreatic tumor cells." (PMID 25105093, 2014). "The pancreatic cancer cells were seeded at low density on transwell filters above feeder layers, which consisted of parental HEK 293T cells or HEK 293T expressing active or inactive Sulf-2." (PMID 17460759, 2007).
lung adenocarcinoma (8 papers, 2007 to 2016). A carcinoma that arises from the lung and is characterized by the presence of malignant glandular epithelial cells. "We showed for the first time that SULF2 staining of tumor cells was associated with a trend towards worse overall survival in patients with lung adenocarcinomas." (PMID 26882224, 2016). "It has been demonstrated that promoter CpG island methylation of SULF2 is highly prevalent in resected lung adenocarcinomas and is significantly associated with better survival." (PMID 23517622, 2013). "Methylation of the SULF2 promoter has been associated with better survival of resected lung adenocarcinoma patients, and also with a marginal improvement in survival of advanced NSCLC patients receiving standard chemotherapy (hazard ratio = 0.63, P = 0.07)." (PMID 24124496, 2013). "Overexpression of Sulf-2 has been shown to inhibit growth of myeloma tumors and breast cancer xenografts, and Sulf-1 has been associated with poor prognosis in gastric cancer and lung adenocarcinoma." (PMID 24459635, 2014). "In conclusion, in this study we have shown by immunohistochemistry that SULF2 protein is present in the majority of lung adenocarcinomas and in all of the lung squamous cell carcinoma samples we tested." (PMID 26882224, 2016). "In our present study, 20 out of 34 (59%) early stage (I or II) lung adenocarcinoma samples had SULF2 staining." (PMID 26882224, 2016). "Sulf-2 overexpression and pro-oncogenic activity have been demonstrated for a number of tumors, including cancer of poor prognosis such as lung squamous cell carcinoma and lung adenocarcinoma." (PMID 24459635, 2014).
non-small cell lung carcinoma (7 papers, 2013 to 2026). A group of at least three distinct histological types of lung cancer, including non-small cell squamous cell carcinoma, adenocarcinoma, and large cell carcinoma. "In this study, we evaluated SULF2 expression by immunohistochemistry and its association with overall survival in a cohort of patients with non-small cell lung cancer (NSCLC)." (PMID 26882224, 2016). "Increased expression of Sulf1 and Sulf2 in some cancers, including pancreatic adenocarcinomas and non-small cell lung cancers is associated with overactive Wnt signalling." (PMID 25681501, 2015). "In addition, SULF2 expression might be credited as a valuable diagnostic and prognostic biomarker in non-small cell lung cancer." (PMID 32049100, 2020). "In non-small cell lung cancer (NSCLC), miR-527/SULF2 was reported to suppress TGF-β/SMAD signaling pathway and inhibit the epithelial-mesenchymal transition of NSCLC cells." (PMID 33472586, 2021).